TLR2 (toll like receptor 2)
Diseases named in the same sentence as TLR2 in open-access papers (continued):
Sharing a sentence is not in itself a finding about the gene and the disease.
infection (continued). "Indeed, whereas antibacterial defence in TLR2 KO mice was unimpaired during infection with S. pneumoniae D39, infection with S. pneumoniae PLN resulted in enhanced outgrowth in these mice." (PMID 17711480, 2008). "In addition, histopathological analyses of lung tissue slides demonstrated a significantly reduced inflammation in lungs of TLR2 KO mice 6 h after infection with S. pneumoniae D39 or S. pneumoniae PLN." (PMID 17711480, 2008). "TLR2-/- mice were significantly sicker than the other mouse strains 24 h after infection." (PMID 17428319, 2007). "In addition, lung IL10 concentrations were moderately lower in TLR2 KO mice at 24 and 48 h after infection (p < 0.05)." (PMID 17676990, 2007). "Finally, the researchers tested the ability of TLR2- and TLR4-deficient mice to survive after infection with live B. pseudomallei." (PMID 17676990, 2007). "Interestingly, they showed that acute infection is more severe in TLR2−/− TLR9−/− mice than in TLR9−/− mice or either TLR2−/−- or TLR4-deficient mice, albeit not as much as in the overtly susceptible MyD88−/− mice." (PMID 18052532, 2007). "However, compared to wt mice, TLR2-/- mice presented even a reduced influx, CD14-/- mice had an increased influx and TLR2-/-/CD14-/- mice had similar leukocyte numbers as wt mice at 12 h after infection." (PMID 17428319, 2007). "One explanation for the infection-dependent induction of TLR2 might be related to the presence of Gram-positive Streptococcus pyogenes, such as GAS." (PMID 16504163, 2006). "Moreover, a potential interaction between CORO1A and the TLR2 signaling pathway may enhance the bactericidal activity of macrophages during phagocytosis, thereby facilitating pathogen clearance at infection sites." (PMID 40563467, 2025). "Importantly, both CD14 and TLR2 have been suggested for targeted therapy in an infection context." (PMID 41307706, 2025). "The secretion of IL-6 by Brucella-infected macrophages via TLR-2 contributes to activating the innate immune response against the infection; nevertheless, it could reduce the expression of class II MHC molecules (MHC-II) through a negative regulation of the transcriptional modulator CIITA." (PMID 38464511, 2024). "This shedding from macrophages is mediated by proteases in response to activation via protein C kinase, ATP, ligation of TLR2 or dectin-1 or after infection with e.g., Candida albicans, Aspergillus fumigatus, Pneumocystis jirovecii, and E. coli, but the mechanism is unknown." (PMID 39027374, 2024). "Therefore, we assayed whether the human virulent Schu S4 strain similarly dampens MAPK activation and TLR2 signaling via TolC during infection of BMMs, as observed for the LVS." (PMID 37404047, 2023). "Therefore, robust plasmid-mediated TLR2 activation by C. muridarum on epithelial and immune cells could have evolved to provide an analogous benefit by limiting infection and severe disease in the lung." (PMID 37662000, 2023). "In addition to TLR9 activation, an upregulation in the transcription of TLR2, which recognizes microbial proteins and glycolipid structures, has also been observed following rAAV infection, suggesting the potential involvement of TLR2 in innate immunity against rAAV vectors." (PMID 37766208, 2023). "Since previous studies involved only TLR2 response to CyHV-2 infection at a certain point of time or in specific tissues (mainly spleen and head kidney), the response of TLR2 to CyHV-2 in the whole infection cycle and multiple tissues (brain, gill, intestine, liver, kidney, and spleen) is unknown." (PMID 38003793, 2023). "Finally, because early viral restriction was Mtb-infection dose-dependent, we explored whether suppression of viral replication in Mtb-infected mice was mediated through mycobacterial sensing by TLR2 or TLR9." (PMID 37720210, 2023).
infection (continued). "Infection by both the yeast and hypha phases of C. krusei greatly induced the expression of proteins associated with cell death pathways and important components of toll-like receptor (TLR) signaling, including TLR2 and TLR4 receptors, as determined via a Western blotting assay." (PMID 37893947, 2023). "Similarly, it has been described that TLR2 and Dectin-1 recognize the Ysp3 protein and the 1-3-β glucan present in the wall of H. capsulatum, and that they are involved in the defense of the host against infection." (PMID 36294673, 2022). "Therefore, this altered leukocyte behavior suggests that chemokine expression profiles may be different in tlr2 mutant zebrafish after infection by different mycobacterial species." (PMID 36741407, 2022). "Previous studies have also shown that the formation of the TLR2 heterodimer is the initial step leading to significant innate immune responses, development of adaptive immunity to pathogens, and protection from immune sequelae related to infection with pathogens." (PMID 36142648, 2022). "The results showed that L. garvieae colonies could be isolated at 6, 12, 24, and 48 hours after infection with planktonic and biofilm bacteria.For the TLR2, IL-1β gene, we found that it was upregulated at 6, 12, and 24 hours and downregulated at 50 hours after infection in the planktonic group." (PMID 35677656, 2022). "Thus, our results suggest that at early stages SARS-CoV-2 S protein signals inhibit immune responses to the virus allowing it to propagate the infection while in combination with TLR2 signals enhances PAI-1 expression, potentially affecting the local coagulation cascade." (PMID 36389723, 2022). "Although angiogenesis in T. cruzi-infected tissues differs in several aspects from the settings of tumor biology, it will be interesting to know whether the released trypomastigotes might benefit from plasma leakage and TLR2-dependent neovascularization to spread the infection systemically." (PMID 35215131, 2022). "To assess whether the loss of TLR2 and TLR9 affects host control of bacterial dissemination to organs outside the infected femur, we measured CFU burdens in the contralateral femur, kidneys, and liver over a 14-day time course of infection." (PMID 36226943, 2022). "In addition, the authors demonstrated that the treatment of these cells with DNMT inhibitors (1 μM decitabine) has been shown to recover TLR2 expression in oral mucosal cells and also appear to be important in inducing an inflammatory response during infection." (PMID 33921194, 2021). "There is evidence showing that the infection of macrophages with trypomastigotes causes an increase in LD biogenesis in a Toll-like receptor (TLR) 2-dependent mechanism, since this process is not observed in bone marrow macrophages derived from C57BL/6 TLR2 knock out mice (TLR2−/−)." (PMID 35198567, 2021). "Toll-like receptor 2 (TLR2) is a protein that senses pathogen molecules and develops the intracellular signaling in response to a possible infection; a genetic variant that affects the functionality of this receptor could increase the risk of infections." (PMID 33776761, 2021). "To test this hypothesis, we compared infection outcomes in wild-type and Tlr2-/- mice." (PMID 34755600, 2021). "In addition, these findings are supported by our prior study in MyD88 KO mice, where animals were exquisitely sensitive to craniotomy infection, since MyD88 is required for both TLR2 and IL-1R signaling, revealing the consequences of negating redundant bacterial recognition pathways." (PMID 32290861, 2020). "Importantly, reduced TLR2 surface expression following infection may also mirror the release of soluble TLR2, the levels of which were shown to be elevated in some infection and inflammatory conditions." (PMID 32576819, 2020).
infection (continued). "Moreover, therapeutic success of TLR2 agonists to combat infections and tumors may be improved if the conditions required for optimal recruitment and activation of NK cells are taken into consideration." (PMID 32696994, 2020). "Upon activation, TLR2 triggers inflammatory signaling pathways, resulting in increased expression and secretion of various antimicrobial peptides, cytokines, and chemokines, which recruit immune cells to the site of infection and trigger the adaptive immune response." (PMID 33256638, 2020). "Moreover, we cannot exclude the possibility that TRIF could be induced later, or by TLR2 activation by lipoproteins upon infection, as illustrated by the Leptospira-induced production of NO in C3H/HeJ TLR4-defective mice." (PMID 32790743, 2020). "Therefore, TLR2 may be another receptor that mediates the secretion of inflammatory cytokines in PmCQ2 infection." (PMID 32922380, 2020). "Furthermore, our previous study also showed that the expression of TLR2 was dramatically changed with the prolonged infection, which suggested that TLR2 might be involved in this dramatically immunological change." (PMID 33044969, 2020). "Therefore, the aims of this study were to assess TLR2 expression and associated host cytokine responses during the course of SAB, and to examine how they differ on the basis of clinical outcomes of SAB at different stages of the infection." (PMID 33256638, 2020). "The reduction in internalization is not due to the lack of recognition of S. aureus by bMECs, because the MA of TLR2 (the main innate response receptor that recognizes S. aureus) was enhanced in the presence of the hormones with relation to control bMECs, which was maintained upon infection." (PMID 32605209, 2020). "However, neither TLR-2−/− nor TLR-4−/− mice were more susceptible to infection, in contrast to the poor cytokine responses of peritoneal macrophages to spherules from TLR-2−/− mice." (PMID 32545735, 2020). "Thus, release of microbial TLR2 agonists during peripheral infections may lead to their entering the CNS to activate directly local microglia and induce neurotoxicity." (PMID 32059733, 2020). "Also, in C57BL/6 TLR2−/− mice infected with Leishmania amazonensis, the parasite burden is reduced when compared with C57BL/ 6 wild type mice which were more susceptible to the infection." (PMID 31119102, 2019). "Thus, the impaired activities of brain cells may have resulted in increased parasite numbers in the brains of the TLR2-/- mice at 30 days post infection." (PMID 31404078, 2019). "Thus, compared with the TLR2+/+ mice, the tachyzoites that escaped periphery immunity in the TLR2-/- mice may have reached the CNS during the acute infection stage." (PMID 31404078, 2019). "Additionally, we found using quantitative real-time PCR that application of β-glucan significantly enhanced the expression of Toll-like receptor (TLR) 2, interleukin (IL)-1β and iNOS at 2 dpi (days post infection) and reduced the increase of TLR2, IL-1β and iNOS induced by Leptospira at 5 dpi." (PMID 31675378, 2019). "The TLR2 gene could influence the prevalence of B. afzelii by different mechanisms such as preventing systemic infection and/or spirochete clearance following infection." (PMID 31040326, 2019). "One of the factors that could modify H. pylori infection is genetic predisposition; single nucleotide polymorphisms (SNPs) in TLR genes, such as TLR1, TLR2, TLR4 and TLR10, were shown to alter the bacterial binding, thereby modulating the risk of infection and subsequent cancer." (PMID 30641993, 2019). "Therefore, Txnip exhibits TLR2-dependent proteasomal degradation during infection." (PMID 31620121, 2019). "The up-regulation of TLR2 and TLR3 may confer an enhanced ability for pathogen recognition, whereas their reduced expression may lead to an inadequate response and therefore an increased risk of infection." (PMID 30374345, 2018).
infection (continued). "Accordingly, employing a murine model of S. mansoni infection we have recently demonstrate that TLR2-dependent pathways activated in vivo by schistosomal-derived lipids play an important immunomodulatory role contributing to the pathogenesis and lethality in the chronic phase of infection." (PMID 30740113, 2018). "Interestingly, our studies suggest that the weight of infected mouse was decreased from the first day post-infection to the ninth day post-infection, and then increased gradually in infected WT mice compared with infected TLR2−/− mice and PBS control mice, which is different from previous results." (PMID 28979269, 2017). "Thus, iNOS/NO responses induced by C. sinensis might also be associated with hepatobiliary tissue damages in TLR2 mutant C57BL/6 J mice and their susceptibility to infection." (PMID 28784165, 2017). "As expected, the absence of TLR2 or TLR4 did not alter the susceptibility of the macrophage to the infection, suggesting that the cellular signaling through these innate immune receptors, mainly TLR2 and TLR4, is required for IL-27p28 production during T. cruzi infection." (PMID 29033934, 2017). "A study performed in 88 infants and 63 adults infected postnatally with HCMV, and in 28 healthy neonates and 50 healthy adults, may suggest a possible protective role of CT heterozygotic status in TLR2 2029 C>T locus against the infection development among adult patients." (PMID 28118851, 2017). "Therefore, based on the present findings, Pam3CSK4 TLR2 agonist might be used as an adjuvant in future vaccine development having an impact on controlling this infection." (PMID 28288677, 2017). "In the present study, because DenV2 infection drove TLR2/MyD88 pathway-dependent Th2-biased immune responses that might facilitate secondary infection with different DenV serotypes, we performed neutralization and ADE assay using Vero cells and BM cell-derived macrophages as targets, respectively." (PMID 29285314, 2017). "Although OspC, a B. burgdorferi lipoprotein that is extensively expressed during early mammalian infection in the skin, is undoubtedly implicated in the recognition of B. burgdorferi by DCs, we have shown that it is not crucial to the TLR2-mediated migration in this model." (PMID 27695100, 2016). "Therefore, chlamydial pre-infection could stimulate such a robust immune response through the activation of TLR2 prior to HSV-2 infection that HSV-2-related disease progression and viral replication are thwarted." (PMID 26726882, 2016). "Importantly, tlr2-null mice were previously reported to exhibit exaggerated immune responses to high dose (500 CFUs, as in the current study) mycobacterial infection but displayed dispersed granuloma, reduced bacterial clearance and succumbed to infection." (PMID 27532872, 2016). "While the mechanism of PE_PGRS33-mediated entrance needs to be better defined, it can be hypothesized that interaction of PE_PGRS33 with the TLR2 on macrophages in the early steps of infection activates an inside-out signalling which contributes to Mtb entry through the CR3 receptor." (PMID 26978522, 2016). "Additionally, in primary human CD4+ T cells we tested whether neutralizing TLR2 using 1 or 5 μg/mL TLR2-specific antibodies could inhibit infection." (PMID 26347747, 2015). "Interestingly, expression of the gene coding TLR2 increased in dendritic cells after infection of susceptible mice with P. brasiliensis, but not in the resistant ones." (PMID 26543326, 2015). "TLR2 expression is induced by LPS and it has been proposed that upregulation of TLR2 by low levels of bacterial products can contribute to the mechanisms by which the immune system increases its response to an infection, with a probable amplification of TLR4 signaling in response to LPS." (PMID 26347203, 2015).
infection (continued). "However, it is to be noted that the major attractor obtained in the TLR2 knock-out scenario is the infection-free attractor (...110...), while only a small fraction reaches the attractor (...100...), where although the NO production is high, both the Th1 and the Th2 responses gets downregulated." (PMID 26660865, 2015). "Finally, infection of primary human macrophages with S. pyogenes in the presence of a TLR2-blocking antibody revealed that the cells were responding under conditions of TLR2 inhibition." (PMID 25756897, 2015). "Therefore, to further explore the effect of P5 on innate inflammatory responses, we used real-time RT-PCR to assess expression of the pattern recognition receptor TLR2 induced in HKs in response to P. acnes (1x108 CFU/ml) infection and then tested the effect of 1.6 μM P5." (PMID 26197393, 2015). "We reasoned that miR-UL112-3p might down-regulate TLR2 as it accumulates during infection." (PMID 25955717, 2015). "Interestingly, TLR2 priming resulted in diminished IL-6 mRNA following infection." (PMID 23853595, 2013). "In addition, it is notable that CD36 protein clearly appeared on the surface of hepatocytes in both WT and TLR2-deficient mice at 2 d post-infection along with a corresponding increase in gene expression, suggesting that TLR2 is not required for this process." (PMID 24058538, 2013). "Besides CR3, TLR2 is also involved in Akt activation following Schu S4 infection." (PMID 23359218, 2013). "More recently, it was reported that TLR2-deficient mice are also less susceptible to the infection with L. amazonensis than the wild-type C57BL6 counterpart, as evidenced by lower parasite burden and reduced recruitment of inflammatory cells in the first weeks of infection." (PMID 22523644, 2012). "Although previous clinical studies have shown that infection with M. tuberculosis or vaccination with M. bovis BCG systemically activate TLR2-mediated pathways, more work is needed to determine whether these responses lead to enhanced HIV susceptibility in humans as suggested by our ex vivo model." (PMID 22844428, 2012). "Another point that might be considered as a prospective target for anti-arenaviral therapy is the Toll-like receptor 2 (TLR2) pathway that activates host defense mechanisms in order to prevent and eradicate infections and participates in the generation of the adaptive immune response." (PMID 23170173, 2012). "Therefore, survival from HSV-1 encephalitis is determined not only by lytic viral infection but also by the balance between pro-inflammatory and down-regulatory anti-inflammatory mechanisms (as well as anti-viral signaling pathways) that limit the pro-inflammatory TLR2 response to infection." (PMID 23082204, 2012). "TLRs/MyD88 was required for inflammasome assembly after infection [vaccinia virus (TLR2/6), Candida albicans (TLR2), Vibrio (MyD88)] and stimulation with DAMPs [biglycan (TLR2/4)], environmental particles [alkane particles (TLR2)] or fungal components [zymosan and mannan (TLR2)]." (PMID 22295065, 2012). "Using this in vitro infection, neutrophils from mice deficient in TLR2, NOD2 or FPR1 produced significantly less IL-1β protein (40, 43 and 37 percent decrease, respectively) in response to S. aureus, suggesting that activation of TLR2, NOD2 and FPR1 promoted neutrophil production of IL-1β." (PMID 23209417, 2012). "The high multiplicity of infection used by the authors of that study, which was higher than those used in the present study, could have forced the infection to proceed more rapidly, thereby masking the role of TLR2 in rapid inflammasome activation." (PMID 21698237, 2011). "Moreover, in more than half of the TLR2-deficient mice, we observed prominent, well-developed bronchus associated lymphoid tissue (BALT) containing CD19-expressing B lymphocytes at 5 days post infection, consistent with inducible BALT (iBALT)." (PMID 21695078, 2011).